IL1B (interleukin 1 beta)
Diseases named in the same sentence as IL1B in open-access papers (continued):
Sharing a sentence is not in itself a finding about the gene and the disease.
infection (continued). "Analysis of the IL-1β level in the sera of mice infected with E. coliCNF1+ indicated that they exhibited a 3-fold higher response and better resistance to infection than those infected with isogenic E. coliCNF1-." (PMID 25781937, 2015). "In this study, we documented significantly increased pro-inflammatory cytokines including TNF-α, IL-17, IL-6 and IL-1β in serum at 6 wks post-infection, at which time mating occurred." (PMID 26322971, 2015). "The pro-inflammatory genes TNF-α and IL-1β are induced by the activation of NF-κB following LPS-induced infection." (PMID 26572495, 2015). "The focus of several studies was a parasite-mediated dysregulation of IL-1β on a transcriptional level after infection of human or murine phagocytes." (PMID 26114647, 2015). "We found that pre-infection with live C. burnetii inhibited the secretion of IL-1β in response to infection with WT Lp, and abolished the secretion of IL-1β in response to infection with flaA−L." (PMID 26687278, 2015). "Among the genes present in this overlap were interleukin 1 beta, a proinflammatory cytokine shown to be involved in infection-related PTB and PE, and superoxide dismutase 2, an antioxidant enzyme shown to be involved in oxidative stress associated with PTB." (PMID 26044726, 2015). "We found that C. burnetii pre-infection inhibits caspase-1 activation and IL-1β processing in response to either WT Lp or flaA−L." (PMID 26687278, 2015). "In the case of Leishmania parasites the importance and the role of inflammasomes and IL-1β is very controversially discussed, mainly due to the use of different Leishmania species, different leishmanial developmental stages and different infection models." (PMID 26114647, 2015). "The cytokines IFN-alpha, IFN-gamma, IL-1β and IL-6 became significantly induced following infection with NDV-CA02 in chicken splenocytes in vitro during early-phase post-infection." (PMID 26635752, 2015). "On the other hand, infection by S. Typhimurium is characterized by a lesser level of IL-17 but a higher level of IL-1β compared to S. Enteritidis infection." (PMID 26075186, 2015). "Rig-1, Mda5, and Tlr3 are involved in the host immune response to DTMUV, and the expression of proinflammatory cytokines (Il-1β, –2, –6, Cxcl8) and antiviral proteins (Mx, Oas, etc.)are also upregulated early in infection." (PMID 26005441, 2015). "IL-1β and IL-18 are powerful proinflammatory cytokines that have been shown to be protective in a large number of experimental infection models." (PMID 25768794, 2015). "In the thymus, the expression level of pro-inflammatory cytokine IL-1β was slightly upregulated compared to the uninfected control following SS-10 or NH-10 infection at 24 and 48 hpi." (PMID 26635752, 2015). "Expressions of IL-1β protein in the 1-MT treated mice were significantly increased at 3 days and 5 days after infection compared with PBS-treated mice, although partly restored at 5 days after infection." (PMID 26361229, 2015). "Infection of adherent monocytes with EBOV in vitro resulted in secretion of IL-1β and IL-6, along with the chemokines IL-8 and RANTES." (PMID 26512687, 2015). "We further examined the production of inactive pro-IL-1β (p31) and mature active IL-1β (p17) in supernatants and cell lysates using immunoblotting after infection." (PMID 26052324, 2015). "Inflammasome activation is an important mediator of host inflammatory responses and has been shown to be important to controlling infection with a number of pathogens, primarily through the secretion of IL-1β and IL-18." (PMID 25781467, 2015). "Infection of wildtype BMDM with other pathogens also resulted in detectable IL-1β in culture supernatants." (PMID 26659062, 2015). "Monocytes promote the early host response to infection releasing key pro-inflammatory cytokines, such as IL-1β." (PMID 26508369, 2015).
infection (continued). "If an infection does take hold, neutrophil recruitment to the site of infection has been demonstrated as crucial for subsequent protection, mediated by pro-inflammatory cytokines such as IL-1β and by IL-17, the product of a TH17 adaptive response." (PMID 25901897, 2015). "After 30 minutes of infection, there was a significant increase in IL-1β release to medium, which was even greater at 60 minutes of infection." (PMID 26267804, 2015). "In particular, elevated IL-1β and IL-6 serum levels have been identified as markers of severity in acute lung injury during infection by the influenza A (H1N1) pdm09 virus, specifically among patients who do not respond to conventional antiviral treatments." (PMID 26657940, 2015). "Infection of MH-S cells with S. marcescens resulted in the detection of IL-1β in culture supernatants." (PMID 26659062, 2015). "There were basically one-peak and two-peak expression patterns of IL-1β in the four tissues during infection." (PMID 25988382, 2015). "The expressions of IL-1β and IL-6 mRNA were down-regulated at 5 days after infection when comparing with A. fumigatus infection at 3 days in the 1-MT treatment group as well as in the PBS treatment group." (PMID 26361229, 2015). "Our results show that MyD88 proinflammatory cytokines (TNF-α and IL-1β) and transcriptional and translational products, increase after infection." (PMID 26021751, 2015). "We found that pre-infection of BMDMs with C. burnetii for 24 h resulted in reduced caspase-1 activation and pro-IL-1β cleavage in response to a second infection with L. pneumophila." (PMID 26687278, 2015). "Inflammation mediated by the inflammasome and the cytokine IL-1β are some of the earliest and most important alarms to infection." (PMID 26500655, 2015). "Prior work has shown that exercise reduces hippocampal levels of IL-1β both basally and following an infection in aged rats." (PMID 26224094, 2015). "For example STAT1 can be activated by type I interferon, STAT3 can be activated by growth factors (e.g. EGF, LIF) and NFκB can be activated by reactive oxygen species, infection and other inflammatory cytokines, including IL-1β." (PMID 26678048, 2015). "Interferon (IFN)-γ and interleukin (IL)-2 increased significantly (p < 0.05 and 0.01) and IL-1β was also increased by infection with nahG parasites (p < 0.05)." (PMID 26466097, 2015). "LCMV infection induced a very good titer of all the major proinflammatory cytokines (TNF, IL12p70, IL1β, IL-6) by day 7 that gradually decreased as infection proceeded." (PMID 26322025, 2015). "Pre-infection with L. mexicana and L. major, revealed a parasite-dependent block of IL-1β maturation and release." (PMID 26114647, 2015). "Using a variety of in vitro and ex vivo intoxication and infection models, we found that LukAB activates Caspase 1, promotes IL-1β secretion and induces necrosis in human monocytes." (PMID 26069969, 2015). "The expression levels of IL-36α, β, γ, IL-1β, TNF-α and IFN-γ mRNA were next determined in the lungs of WT and TNF-α deficient mice at different time-points following aerogenic infection with M. tuberculosis." (PMID 25950182, 2015). "Infection-associated induction of pro-inflammatory cytokines such as IFN-γ, TNF and IL-1β poses a double-edged sword." (PMID 26260055, 2015). "The expression of five antiviral genes, including pro-inflammatory cytokines IL-1β and osteopontin (OPN), was altered by both age and infection, while age was associated with the expression of 15 antiviral genes." (PMID 24558422, 2014). "Consistent with our intracellular cytokine staining and Western blot data, the highest levels of IL-1α and IL-1b synthesis were detected between 5–6 hrs post-infection." (PMID 25058342, 2014). "Here we show that the detrimental role of IL-1β during infection with B. pseudomallei (and closely related B. thailandensis) is due to excessive recruitment of neutrophils to the lung and consequent tissue damage." (PMID 25166912, 2014).
infection (continued). "To study il1b transcription upon infection, we injected fluorescent bacteria (E. coli-DsRed) into the notochord of Tg(il1b:GFP-F) embryos." (PMID 24973754, 2014). "The RT-PCR and ELISA data indicated that FK506-treated mice exhibited a reduced expression level of IL-1β at 1 day post-infection (P<0.05, and P<0.05, respectively)." (PMID 25464008, 2014). "EV-A71-infected cells treated with LiCl at various concentrations were examined for IL-6 and IL-1β production at 48 h post-infection." (PMID 25412347, 2014). "Expression of GM-CSF, TNFα, IP10 and IL-1β peaked on day 5 post infection and gradually declined over time." (PMID 24699832, 2014). "Using murine models, we previously demonstrated that during B. pseudomallei infection, production of IL-1β is deleterious as it recruited excessive neutrophils to the site of infection." (PMID 25166912, 2014). "IL-1β plays a pivotal role in mediating host response to infection and danger molecules, and is released and secreted via inflammasome-dependent caspase-1 activation." (PMID 25000410, 2014). "The production of IL-1β is important for the proper development of antimicrobial adaptive immunity during the initial stages of infection." (PMID 25329476, 2014). "IL-1β governs the recruitment of inflammatory cells such as neutrophils to the site of infection and is important in the generation of optimal adaptive immunity." (PMID 24701032, 2014). "We examined the levels of TNF-α, IFN-γ, IL-1β, and IL-6 in the kidneys of untreated or EtOH-treated mice and uninfected or infected with Ab at 72 h post-infection." (PMID 24752133, 2014). "Antiviral and pro-inflammatory cytokine expressions (IFN-β and IL-1β as representative cytokines) in the blood were sequentially studied throughout the infection." (PMID 24460592, 2014). "This is consistent with the fact that the up-regulation of different cytokine encoding genes such as IL-1β, TNFα and CCL4 by MEC is restricted at the very early stages of infection, before a decrease at 30 hpi." (PMID 24521038, 2014). "We performed a relative RT-qPCR to study the changes in IFN-β and IL-1β mRNA transcription after the infection with IAV, using the 28S gene as the housekeeping gene." (PMID 24460592, 2014). "This locus appeared also to decrease the production of the proinflammatory cytokine IL-1β after in vitro infection." (PMID 24505352, 2014). "Since IL-1β and OPN were statistically significant during early time points in A2 infection (1–3 dpi) and associated with older age, we examined them further at 5 and 8 dpi with mucogenic RSV strains in lung tissue and fluids." (PMID 24558422, 2014). "NLRP3−/− macrophages were not refractory to T. cruzi, and instead exhibited a very high basal level of ROS (>100-fold higher than WT controls) that was maintained after infection in an IL-1β-independent manner and contributed to efficient parasite killing." (PMID 25372293, 2014). "The microarray analysis of splenocytes from C57BL/6 at 6 days post-infection demonstrates enhanced expression of various genes from the inflammasome pathway, including Casp1 and Il1b." (PMID 24453977, 2014). "Three hours post-infection, a significant increase in KC, IL-1β, TNFα, and IL-6 levels was detected in BALs from TLR9-/- compared to WT mice." (PMID 24595157, 2014). "This is in contrast to recent evidence that suggested IL-1β expression and secretion after infection of human trophoblasts with C. trachomatis was dependent upon intracellular NOD1." (PMID 25010668, 2014). "In other experimental conditions, recent findings showed that the production and secretion of the proinflammatory cytokine IL-1β was significantly enhanced in p62−/− macrophages after infection with Legionella pneumophila." (PMID 25169902, 2014). "As expected, p65 translocated into the nucleus in mock-infected cells that had been stimulated with TNF-α or IL-1β, and this was inhibited in the presence of vv811WT infection." (PMID 24371075, 2014).
infection (continued). "The expression level of IL-1β in VK627 infection group was very significantly higher than rVK627E group at 3, 5 and 6 dpi (P < 0.01)." (PMID 25547136, 2014). "Inflammation is a natural response to damage and/or infection that are mediated by pro-inflammatory cytokines including interleukin 1 beta (IL-1β), interleukin 6 (IL-6), and tumor necrosis factor alpha (TNFα)." (PMID 25228881, 2014). "The NLRP3 inflammasome is a molecular platform that is activated upon cellular infection or stress and triggers the maturation (activation) and secretion of IL-1β, to engage the inflammatory response." (PMID 25216263, 2014). "IL-1β and IL-6 were then showing up, presumably to sustain the inflammatory response, with a ‘mirror’ image of their respective increase all along infection." (PMID 24637903, 2014). "For the MP287/03 Mbv infection, comparable low levels of IL-1β were found in cell supernatants from C57BL/6 and P2X7R−/− mice, but the lack of P2X7R resulted in an increase of IFNγ and a decrease of IL-10." (PMID 24991816, 2014). "Pre-stimulation with poly(I∶C) followed by L. pneumophila infection increased Il1β transcription initially (after 2 hrs of infection) in wild type macrophages compared to cells that were untreated (compare black bars with grey bars)." (PMID 25058342, 2014). "Surprisingly, this was reversed by 6 hrs post infection and cells that were pre-treated with poly(I∶C) down regulated their Il1β transcription." (PMID 25058342, 2014). "Upon RSV rA2-L19F-infections, IL-1β is diminished in aged mice compared to young on days 1 and 5 dpi; by 8 dpi, levels are comparable between age groups." (PMID 24558422, 2014). "The present studies point to the rapid induction of IL-1β in conjunction with inflammasome activation within brain macrophage lineage cells in response to infection by HIV-1 (and FIV)." (PMID 24886384, 2014). "To specifically determine if NLRP3 inflammasome activation by ASC/caspase-1 is the primary source of protective IL-1β in the context of Tc infection, we conducted further studies in primary bone marrow-derived mφs from NLRP3-/- mice and matched controls." (PMID 25372293, 2014). "Confirming what we observed during infection with B. pseudomallei, production of IL-1β following infection with B. thailandensis was dependent on NLRP3, ASC, and caspase-1 while pyropotosis was dependent on NLRC4." (PMID 25166912, 2014). "The cytokine interleukin-1 (IL-1) has two main pro-inflammatory forms, IL-1α and IL-1β, which are central to host responses to infection and to damaging sterile inflammation." (PMID 24790078, 2014). "Because the IL-1R signaling pathway is required for clearance of B. pertussis and rapid vaccine-mediated immunity, it was suggested that NLRP3-inflammasome activation of IL-1β would be required for controlling infection." (PMID 25198773, 2014). "Compared to the MS_Vec, mRNA levels of TNF-α and IL-1β were significant upregulated in macrophages after 12 hours of infection with MS_Rv3402c." (PMID 24722253, 2014). "During infection, expression of IL-1β is often induced downstream of the Toll-like receptors through translocation of the transcription factor NF-κB." (PMID 25198773, 2014). "Future studies looking at alternative cleavage mechanisms will help to identify how IL-1β is processed during infection." (PMID 25198773, 2014). "Infection of bone-marrow macrophages with virulent (Dot+) L. pneumophila induced Il1α, Il1β and Tnfα transcripts by 6 hrs post infection." (PMID 25058342, 2014). "IL-1β and IL-6 are key mediators of host response to infections and powerful pro-inflammatory cytokines involved in a diverse range of inflammatory and infectious conditions." (PMID 24796752, 2014). "In the lesions, there was an increase in IL-1β mRNA expression all over the infection course, from day 2 to day 360 p.i., with a peak at 60 days p.i.." (PMID 24637903, 2014).
infection (continued). "The first aim of this study was to determine the effect of silibinin on infection (LPS) and inflammation (IL-1β) induced pro-labour mediators in human fetal membranes and myometrium." (PMID 24647589, 2014). "Given that IL-1β mediates the efficient clearance of B. pertussis from the lungs, we also expected the inflammasome to be required for control of the primary infection." (PMID 25198773, 2014). "For the infection group, mean IL-1β and IL-10 concentrations in PBMC culture media were significantly lower than for the control group." (PMID 25252649, 2014). "Young mice produced significant levels of IL-1β upon infection with either rA2-L19F and 2-20 by 4 or 5 dpi; levels remained significantly elevated at 8 dpi." (PMID 24558422, 2014). "The immunohistological results showed that the positive cells of NLRP3, IL-1β and TNF-α altered the positive levels of original cells in tissues and infiltrated inflammatory cells which caused by H9N2 infection." (PMID 25547136, 2014). "In the late phase of infection (on days 19 and 26), 5-LO−/− spleen cells, in contrast to what was observed for WT spleen cells, showed a sustained elevation in the production of IL-1β and IL-10, higher levels of IL-12, and lower levels of IFN-γ." (PMID 25165415, 2014). "Inflammasomes are multi-protein complexes that have gained attention for their capacity to link the sensing of infection or injury with subsequent inflammatory caspase activation and ensuing cleavage and release of the inflammatory cytokines, IL-1β and IL-18." (PMID 24886384, 2014). "In the liver tissue, IL-1β mRNA expression increased later, from 2.9-fold at day 30 to 4.7-fold at day 90, and was at its maximum at the middle stage of infection." (PMID 24637903, 2014). "Less IL-1β and KC were found at 3 hours for the resistant mice (S/C-KO), as well as less IL-10 both at 1.5 and 3 hours post-infection." (PMID 24498223, 2014). "We have shown that pro-IL-1α and pro-IL-1β accumulate in cells that harbor L. pneumophila between 4–6 hrs post infection, despite a significant block in protein translation." (PMID 25058342, 2014). "The role of miR-146a in regulating NF-κB activation was consistent with the observed defect in downregulation of NF-κB-dependent cytokines and chemokines IL-1β, IL-6, Cxcl1 and Cxcl2, in B6 miR-146a−/− mice at 4 weeks post-infection." (PMID 24967703, 2014). "The NLRP3 inflammasome is the most characterized inflammasome complex and involved in IL-1β maturation during infections with several viruses." (PMID 24966466, 2014). "The kinetics of pro-IL-1α and pro-IL-1β production in infected cells indicated that there was enhanced accumulation of these proteins between 4–6 hrs post-infection." (PMID 25058342, 2014). "IL-1β is considered an “alarm” cytokine and has been shown to be critical for host defense against infection." (PMID 25010102, 2014). "We measured pro-inflammatory cytokine response (TNF-α, IFN-γ, IL-1β, and IL-6) in the lungs of untreated or EtOH-treated mice and uninfected or infected with Ab at 4, 24, 48, and 72 h post-infection." (PMID 24752133, 2014). "In macrophages of both mouse strains IL-1β concentrations were significantly higher in response to B. pseudomallei E8 compared to B. thailandensis E264 infection." (PMID 24626296, 2014). "ΔripA bound to beads and typical ΔripA infections elicit similar levels of IL-1β, even though the cells infected with beads should contain more bacteria initially (data not shown)." (PMID 24505427, 2014). "In order to characterize the effect of immunization with the inactivated LPS deficient vaccine on cytokine levels, sera were collected from vaccinated and control mice 12 h post-infection and the levels of IL-1β, IL-6 and TNF-α were determined." (PMID 25485716, 2014). "Infection of type II P.gingivalis also exhibited prolonged cytokine response such as IL-1b, IL-8 and TNFα." (PMID 24466164, 2014).